LRBA (LPS responsive beige-like anchor protein)
Description:
Involved in coupling signal transduction and vesicle trafficking to enable polarized secretion and/or membrane deposition of immune effector molecules (By similarity). Involved in phagophore growth during mitophagy by regulating ATG9A trafficking to mitochondria.
Synonyms: BGL; CDC4L; LBA; LAB300; uc.147; CVID8
Tractability: Small molecule: it has a high-quality binding pocket. Antibody: UniProt places it where antibodies can reach, with medium confidence; UniProt predicts a signal peptide or a membrane-spanning region; its Gene Ontology location is reachable by antibodies, with medium confidence. PROTAC: ubiquitination databases record sites on it; its protein half-life has been measured.
Gene: Protein-coding gene on chromosome 4 (150,264,435 to 151,015,755, reverse strand). Ensembl gene ENSG00000198589.
Subcellular location: Cell membrane; Endoplasmic reticulum membrane; Golgi apparatus, trans-Golgi network membrane; Lysosome membrane
Subcellular location (Human Protein Atlas): Golgi apparatus; Cytosol
Gene Ontology:
Molecular function: protein binding; protein kinase binding
Biological process: mitophagy; protein localization to phagophore assembly site
Cellular component: Golgi apparatus; membrane; cytosol; endoplasmic reticulum membrane; lysosomal membrane; plasma membrane
Genetic constraint (gnomAD): Loss-of-function variants: 75 observed, 176.57 expected, observed/expected ratio (o/e) 0.42, 90% interval 0.35 to 0.51. The upper end of that interval is the gene's LOEUF score, 0.51, which puts it in group 2 of 6, group 1 being the genes least tolerant of losing a copy. Missense variants: 2,210 observed, 2,392.9 expected, observed/expected ratio (o/e) 0.92, 90% interval 0.89 to 0.96. Synonymous variants: 851 observed, 850.43 expected, observed/expected ratio (o/e) 1, 90% interval 0.94 to 1.06.
Gene-disease validity (ClinGen):
ClinGen rates the evidence that LRBA causes each of these diseases.
combined immunodeficiency due to LRBA deficiency (autosomal recessive): Definitive.
Homologues: Orthologues: macaque LRBA (98% identical), dog LRBA (92% identical), rabbit LRBA (91% identical), mouse Lrba (91% identical), pig LRBA (91% identical), rat Lrba (90% identical), guinea pig LRBA (89% identical), zebrafish lrba (71% identical), tropical clawed frog lrba (70% identical), Caenorhabditis elegans sel-2 (37% identical), chimpanzee LRBA (26% identical), Caenorhabditis elegans wdfy-3 (14% identical). Paralogues in human: NBEA (64% identical), NBEAL1 (19% identical), NBEAL2 (18% identical), WDFY3 (16% identical), WDFY4 (16% identical), LYST (15% identical), NSMAF (9% identical).
Diseases named in the same sentence as LRBA in open-access papers:
LRBA is named in the same sentence as 88 diseases in open-access papers, as found by Europe PMC text mining. Sharing a sentence is not in itself a finding about the gene and the disease. The quoted sentences say what the papers report.
Autoimmunity (27 papers, 2014 to 2026). The occurrence of an immune reaction against the organism's own cells or tissues. "LRBA deficiency is associated with an inborn error in immunity characterized by immunodeficiency and autoimmunity." (PMID 39076990, 2024). "Lipopolysaccharide (LPS)-responsive beige ankyrin (LRBA) gene mutations were first reported as the cause of immunodeficiency syndromes and autoimmunity in 2012." (PMID 39108694, 2024). "In humans, LRBA deficiency results in an extended phenotype that includes recurrent infections, autoimmunity, lymphoproliferation, and splenomegaly." (PMID 39076990, 2024). "Mutations resulting in LRBA deficiency cause common variable immunodeficiency-8 with autoimmunity, which can include coughing, respiratory infections, bronchiectasis and interstitial lung disease." (PMID 36914875, 2023). "Clinical and genetic characterization of kindreds containing individuals who have homozygous or compound heterozygous inactivating LRBA mutations has revealed a crucial role for this gene in preventing autoimmunity in humans." (PMID 35603158, 2022). "The data presented in this study suggest that the patho-etiology of DM in some of LRBA-deficient patients is unrelated to the severe autoimmunity seen in these patients." (PMID 35453810, 2022). "Patients with mutations in the LRBA gene (encoding the lipopolysaccharide-responsive and beige-like anchor protein) have a syndrome of lymphoproliferation, humoral immune deficiency, and autoimmunity; they also show CTLA4 loss." (PMID 33435309, 2021). "Further functional studies in LRBA deficiency are necessary to provide detailed information on the origin of autoimmunity in order to develop reliable predictive biomarkers for affected patients." (PMID 27683652, 2016). "Another gene of interest on chromosome 15 is LRBA as deleterious mutations in LRBA have been associated with a syndrome of immune deficiency and autoimmunity in people." (PMID 25393235, 2014). "Considering that LRBA deficiency may contribute to autoimmune disorders in patients, targeted therapy with subcutaneous injection of abatacept at a dosage of 125 mg/w was administered for 5 months prior to transplantation." (PMID 39108694, 2024). "The key player, CTLA-4, which was found to be defective in LRBA-deficient patients, was hypothesized to play an important role in developing autoimmunity in these patients, such as T1DM." (PMID 35453810, 2022). "LRBA is an important gene that is involved in a syndrome of immune deficiency and autoimmunity." (PMID 31533607, 2019). "LRBA deficiency thus also results in reduced CTLA4 expression, impairing immunoregulation and predisposing patients to autoimmunity." (PMID 41515894, 2025). "LPS-responsive beige-like anchor protein (LRBA) deficiency is a primary immunodeficiency disease (PID) characterized by a regulatory T cell defect resulting in immune dysregulation and autoimmunity." (PMID 37443020, 2023). "These include LRBA, a member of the same BEACH domain family as NBEAL2, recessive mutations of which cause autoimmunity and lymphocytic infiltration through defective CTLA-4 trafficking." (PMID 37349339, 2023). "We screened all participants for the seven genes known to cause monogenic autoimmunity that can include diabetes (AIRE, IL2RA, FOXP3, LRBA, STAT1, STAT3, STAT5B)." (PMID 29417186, 2018). "As LRBA regulates CTLA4 trafficking, its deficiency has been linked to autoimmunity and lymphoproliferation, which could help explain the clinical heterogeneity among carriers of the same FAS variant." (PMID 40755914, 2025). "Furthermore, LRBA deficiency leads to impaired trafficking of CTLA-4 on the Treg cells’ surface, causing disruption of immune homeostasis and leading to autoimmune disorders, organomegaly, and hypogammaglobulinemia." (PMID 36569874, 2022).
Immunodeficiency (20 papers, 2014 to 2025). Failure of the immune system to protect the body adequately from infection, due to the absence or insufficiency of some component process or substance. "Mutations in lipopolysaccharide-responsive vesicle trafficking, beach and anchor-containing protein (LRBA) cause immune deficiency and inflammation." (PMID 28690850, 2017). "The BEACH protein LRBA has been implicated in immune response and cell proliferation, and human LRBA mutations cause severe immune deficiency." (PMID 28814779, 2017). "A deficiency of LRBA leads to immune dysregulation and immunodeficiency." (PMID 36834508, 2023). "Joint involvement is variable in LRBA deficiency, hence it should always be kept in mind as a differential diagnosis for a patient with combination of juvenile arthritis and clinically atypical immune dysregulation and / or immunodeficiency." (PMID 31847838, 2019). "Mutations in LRBA, a BEACH domain protein, cause severe immune deficiency in humans." (PMID 38724551, 2024). "Since no diagnostic details are given, the exclusion of combined immune deficiencies involving T-cell immunity as well as B-cell failure, or known mutations in monogenic disease (e.g. CTLA4, LRBA, KMT2D, XIAP, RAG1, NFKB1) is unclear." (PMID 33329602, 2020).
primary immunodeficiencies (9 papers, 2017 to 2025). "Primary immunodeficiency diseases (PIDs) are associated with multiple genetic alterations including mutations of the lipopolysaccharide responsive Beige anchor (LRBA) gene." (PMID 40158206, 2025). "Lipopolysaccharide-responsive beige-like anchor protein (LRBA) deficiency is a primary immunodeficiency disease (PID) caused by biallelic mutations in the LRBA gene." (PMID 37443020, 2023). "Many other primary immunodeficiencies with prevailing lymphoproliferation, such as LPS-responsive beige-like anchor protein (LRBA) deficiency and cytotoxic T lymphocyte antigen-4 (CTLA-4) haploinsufficiency, are also associated with decreased or dysregulation of Tregs." (PMID 33613511, 2020). "Bi-allelic mutations in LRBA (from Lipopolysaccharide-responsive and beige-like anchor protein) result in a primary immunodeficiency with clinical features ranging from hypogammaglobulinemia and lymphoproliferative syndrome to inflammatory bowel disease and heterogeneous autoimmune manifestations." (PMID 30410199, 2018). "Furthermore, several heterozygous variants were identified in genes associated with known primary immunodeficiencies that are inherited in an autosomal recessive manner, such as LYST, LRBA, RAG1, EXTL3, and STX11 (Group 4)." (PMID 30723478, 2018).
enteropathy (7 papers, 2017 to 2025). "This implies a possible association between certain LRBA mutations and severe manifestations like enteropathy." (PMID 32154999, 2020). "In some cases, these findings provide clues to the pathogenesis of the complications in CVID, such as mutations in CTLA4, LRBA and BACH2 which have been identified in subjects with severe enteropathy." (PMID 37711607, 2023).
inflammatory bowel disease (7 papers, 2016 to 2025). A spectrum of small and large bowel inflammatory diseases of unknown etiology. "The LRBA deficiency has also been linked in the literature to various other disorders such as neonatal diabetes, polyarthritis, and early-onset inflammatory bowel disease." (PMID 39184709, 2024). "We reported a new pathogenic variant of LRBA deficiency with a complex phenotype—neonatal diabetes, very early-onset inflammatory bowel disease, and polyarthritis—who presented with lymph node enlargement with an RDD diagnosis." (PMID 36569874, 2022). "We reported a new pathogenic variant of LRBA deficiency with a complex phenotype—neonatal diabetes, very early-onset inflammatory bowel disease, and polyarthritis—who presented with lymph node enlargement." (PMID 36569874, 2022). "We herein report a case of LRBA deficiency presenting as neonatal diabetes, very early inflammatory bowel disease (IBD), polyarthritis, and inguinal lymphadenopathy." (PMID 36569874, 2022).
autoimmune lymphoproliferative syndrome (5 papers, 2022 to 2025). Autoimmune lymphoproliferative syndrome (ALPS) is a rare, inherited disorder characterized by non-malignant lymphoproliferation, multilineage cytopenias, and a lifelong increased risk of Hodgkin's and non-Hodgkin's lymphoma. "LRBA deficiency leads to different types of congenital immune deficiencies, such as CVID, autoimmune lymphoproliferative syndrome (ALPS) with recurrent infections, and even sepsis." (PMID 35281010, 2022).
diabetes (5 papers, 2018 to 2026). "Additionally, many LRBA‐deficient patients suffer from at least one autoimmune disorder with autoimmune hemolytic anemia and ITP the most common, followed by autoimmune thyroid disease, autoimmune enteropathy, type 1 diabetes mellitus, and juvenile idiopathic arthritis." (PMID 32154999, 2020).
hypogammaglobulinemia (5 papers, 2021 to 2025). "Moreover, the spectrum of genetic variants identified in our patients—including TNFRSF13B, DOCK8, RAG1, and LRBA—closely resembles the mutational landscape reported in prior studies of CVID and other antibody deficiencies." (PMID 40993545, 2025). "A number of previous studies have outlined the clinical phenotypes of large patient groups with antibody deficiency who have mutations in selected genes, including the TACI gene, CTLA4, NFKB1, NFKB2, STAT3, PI3KCD, or LRBA." (PMID 38274105, 2023). "Pathogenic variants in CTLA4, LRBA, TNFRSF13B (TACI), DOCK8, RAG1, PRF1, PIK3CD, IKZF1, and PRKDC have been identified in patients with AICs and PIDs, often associated with other clinical features such as lymphoproliferation, splenomegaly, and immunologic abnormalities such as hypogammaglobulinemia." (PMID 40993545, 2025). "LRBA deficiency was diagnosed in three patients, all of whom presented with typical features, including autoimmune cytopenia, granulomatous-lymphocytic interstitial lung disease (GLILD), hypogammaglobulinemia, reduced switched memory B cells, and expanded CD21lo B cells." (PMID 39072316, 2024).
autoimmune disease (4 papers, 2022 to 2024). A disorder resulting from loss of function or tissue destruction of an organ or multiple organs, arising from humoral or cellular immune responses of the individual to their own tissue constituents. "LRBA deficiency usually leads to recurrent infections, lymphoproliferative disorders, autoimmune diseases, allergic diseases." (PMID 38719908, 2024).
breast carcinoma (3 papers, 2013 to 2022). "LRBA was the only gene which consistently was correlated with increased breast cancer mortality and disease recurrence when its mRNA was over-expressed in the tissue biopsy (median HR of 1.10 in both OS and DFS)." (PMID 23819905, 2013). "LRBA may be essential for human breast cancer cell survival, as its increased expression is a prominent component of a gene signature that predicts poor prognosis and response to therapy in breast cancer patients." (PMID 35603158, 2022). "Additionally, LRBA was shown to be involved in trafficking key immune checkpoints (e.g., CTLA-4), is known to contribute to immune dysregulation, and is correlated with both disease mortality and recurrence in breast cancer." (PMID 35660939, 2022).
common variable immunodeficiency (3 papers, 2019 to 2024). "Both LRBA and CTLA-4 were identified as causes of monogenic common variable immunodeficiency (CVID) in 2012 and 2014, respectively." (PMID 38535602, 2024).
IPEX syndrome (3 papers, 2021 to 2025). "While present in almost all categories, their burden and distribution vary, with certain defects acting as clear ‘hotspots’, such as IPEX syndrome, APECED, LRBA, RAG1, RAG2, CD3γ, Helios, ARPC1B, and CD55 deficiencies." (PMID 41394846, 2025).
juvenile idiopathic arthritis (3 papers, 2019 to 2021). Juvenile idiopathic arthritis (JIA) is the term used to describe a group of inflammatory articular disorders of unknown cause that begin before the age of 16 and last over 6 weeks. "We herein present a case of LRBA deficiency which initially presented with polyarticular arthritis and was diagnosed with Juvenile Idiopathic Arthritis (JIA)." (PMID 31847838, 2019). "High consanguineous marriages in Arab countries provides an opportunity to find novel risk loci like LACC1 and LRBA that are associated with the monogenic juvenile idiopathic arthritis (JIA) and inflammatory bowel disease with combined immunodeficiency, respectively, in the Arab population." (PMID 34054914, 2021).
rheumatoid arthritis (3 papers, 2017 to 2025). A chronic, systemic autoimmune disorder characterized by inflammation in the synovial membranes and articular surfaces. "While lysosomal dysfunction was described for a plethora of diseases among which are SLE, Sjörgen disease, Crohn’s disease, and rheumatoid arthritis, the enlarged endolysosomes in CHS and LRBA deficiency are functional in terms of protein degradation." (PMID 39325073, 2024).
colitis (2 papers, 2022 to 2025). Inflammation of the colon. "Using a severe form of DSS-induced colitis that is lethal in a minority of wild-type (WT) hosts, we show that LRBA knockout (LRBA KO) mice are uniformly susceptible to DSS-mediated lethal disease." (PMID 35603158, 2022). "An enhanced proinflammatory response in the context of LRBA deficiency has also been reported for Lrba−/− mice, which display increased susceptibility to DSS-induced colitis." (PMID 40550954, 2025). "Analysis of bone marrow (BM) chimeras showed that susceptibility to lethal colitis is primarily due to LRBA deficiency in the immune compartment and not the gut epithelium." (PMID 35603158, 2022).
gastric cancer (2 papers, 2017 to 2018). A primary or metastatic malignant neoplasm involving the stomach. "This is the first description of gastric cancer and malignant melanoma in a young adult with LRBA deficiency." (PMID 28720148, 2017). "In conclusion, to the best of our knowledge, we present the first co-occurrence of gastric cancer and malignant melanoma with LRBA deficiency." (PMID 28720148, 2017). "However, only a single report of gastric cancer was recently described for LRBA deficiency." (PMID 30250467, 2018). "Intriguingly, LRBA deficiency and CTLA4 haploinsufficiency could represent human in vivo models of CTLA4 blockade with checkpoint inhibitors; medicines that actually improved survival in several cancers, particularly in melanoma, but also in gastric cancer." (PMID 28720148, 2017).
respiratory infections (2 papers, 2023 to 2025). "The most common infections observed in the cohort were respiratory infections, especially in patients with LRBA deficiency, whereas patients with FERMT1 deficiency suffered gram-negative sepsis (Escherichia coli, Klebsiella pneumoniae)." (PMID 41142805, 2025).
Splenomegaly (2 papers, 2022 to 2024). Abnormal increased size of the spleen. "While patients with LRBA deficiency can have a similar phenotype to CTLA-4 insufficiency, LRBA deficient patients tend to have high rates of splenomegaly, double-negative T cells and low numbers of Tregs, and decreased plasmablasts." (PMID 36359748, 2022).
Allergy (1 paper, 2025). An allergy is an immune response or reaction to substances that are usually not harmful. "The highest prevalence of allergy was found in patients suffering from genetic disorders caused by variants in DOCK8, CARD11 (AD DN), ARPC1B, and PLCG2, while there were no occurrences of allergy in patients with defects in the LRBA and RAG1 genes." (PMID 41142799, 2025).
Arthritis (1 paper, 2019). Inflammation of a joint. "A thorough search of the literature using PubMed and Medline for data on LRBA deficiency and arthritis revealed details of 7 previously reported patients." (PMID 31847838, 2019).
ataxia telangiectasia (1 paper, 2024). Ataxia-telangiectasia is the association of severe combined immunodeficiency (affecting mainly the humoral immune response) with progressive cerebellar ataxia. "FCM findings provided informative clues, although they lacked specificity for diagnosing hypomorphic V(D)J recombination defects, Ataxia Telangiectasia, CVID, LRBA deficiency, RIPK1 deficiency, and Good’s syndrome." (PMID 39072316, 2024).
autism (1 paper, 2012). Persistent deficits in social interaction and communication and interaction as well as a markedly restricted repertoire of activity and interest as well as repetitive patterns of behavior. "Whereas involvements in autism and obesity may be explained by impacts of NBEA underexpression on the development or functioning of different neuronal circuitries, the association with cancer may be due to functional overlap with its ubiquitous isoform, LRBA." (PMID 22438821, 2012).
autoimmune gastritis (1 paper, 2025). Inflammation of the body fundic mucosa of the stomach. "After excluding H. pylori infection and classic autoimmune gastritis, we propose that the severe global gastric atrophy arises from a unique immunopathological mechanism triggered by LRBA deficiency." (PMID 41378195, 2025).
bone marrow failure (1 paper, 2022). "Neither ALPS nor LRBA deficiency are known for bone marrow failure, but in the related Tregopathy, CTLA4-haploinsufficiency, cytopenias can be due to autoimmunity, as well as to bone marrow failure." (PMID 36119097, 2022).